ENSG00000276859
Gene: Miscellaneous RNA gene on chromosome 20 (58,842,030 to 58,842,132, forward strand). Ensembl gene ENSG00000276859.
Homologues: Orthologues: mouse Gm56457 (42% identical).